FGFR3 (fibroblast growth factor receptor 3)
Diseases named in the same sentence as FGFR3 in open-access papers (continued):
Sharing a sentence is not in itself a finding about the gene and the disease.
achondroplasia (continued). "Antibodies that effectively inhibit FGFR3 activity in vivo would also be potential candidates to treat skeletal dwarfism and other pathologies associated with achondroplasia." (PMID 27056048, 2016). "Genotype- and phenotype-level correlations have been found between the clinical symptoms of achondroplasia and achondroplasia-specific FGFR3 mutations." (PMID 27370225, 2016). "In contrast to the relatively rare incidence of CATSHL syndrome caused by FGFR3 inactivation, activating mutations in FGFR3 that result in achondroplasia and hypochondroplasia occur at an estimated frequency between 1/15,000 and 1/40,000 live births." (PMID 25852647, 2015). "One of the most well-known de novo mutations is FGFR3-G380R, which is detected in more than 98% of patients with achondroplasia." (PMID 26114861, 2015). "Various mouse crosses have demonstrated that transgenic modulation of CNP can rescue mice from achondroplasia caused by disruption of fibroblast growth factor receptor 3 (FGFR3), mitogen-activated protein kinase (MAPK), or PRKG2 signaling." (PMID 25924610, 2015). "Patients with achondroplasia have nonsense genetic mutation in FGFR3 with glycine to arginine substitution at position 380 (G380R), in the transmembrane domain of the receptor." (PMID 25530967, 2014). "Fibroblast growth factor receptor 3 (FGFR3) is the only gene known to cause achondroplasia (ACH), hypochondroplasia (HCH), and thanatophoric dysplasia types I and II (TD I and TD II)." (PMID 25614871, 2014). "Achondroplasia is caused by AD mutations of the transmembrane receptor fibroblast growth factor receptor 3 (FGFR3), an important regulator of linear bone growth." (PMID 25530967, 2014). "Achondroplasia is an AD genetic disorder, where it is linked to mutations of FGFR3 on the distal short arm of chromosome 4." (PMID 25530967, 2014). "Collectively, these observations established the fact that FGFR3 is an important negative regulator of endochondral bone formation and that the mutations cause a constitutive activation of FGFR3, resulting in achondroplasia and related dwarfing phenotype." (PMID 25530967, 2014). "Hypochondroplasia (HCP) and achondroplasia (ACP) are two common skeletal disorders caused by heterozygous mutations in the fibroblast growth factor receptor 3 gene (FGFR3)." (PMID 23149434, 2012). "As the achondroplasia mutation affects ligand-independent FGFR3 signaling, here we focus on ligand-independent dimerization." (PMID 23056398, 2012). "A conceptually similar study of the FGFR3 c.1138G>A achondroplasia mutation (encoding p.Gly380Arg) obtained broadly comparable results, with maximum mutation levels up to 2.3% in testis biopsies." (PMID 22879958, 2012). "Instead, the phosphorylation efficiency within un-liganded FGFR3 dimers is increased, and this increase is likely the underlying cause for pathogenesis in achondroplasia." (PMID 22529939, 2012). "Neonatal FGFR3 mutation screening showed that the newborn was heterozygous for the classic achondroplasia G340R mutation." (PMID 22747519, 2012). "The mutations do not increase the cross-linking propensity of FGFR3, contrary to previous expectations that the achondroplasia mutations stabilize the FGFR3 dimers." (PMID 22529939, 2012). "The Gly380Arg mutation in FGFR3 is the genetic cause for achondroplasia (ACH), the most common form of human dwarfism." (PMID 23056398, 2012). "Our results demonstrate that the two achondroplasia mutations, G375C and G380, have the same effect on FGFR3 activity, supporting the idea that identical degrees and mechanisms of over-activation lead to identical phenotypes." (PMID 22529939, 2012).
achondroplasia (continued). "Gain-of-function alterations of the FGFR3 gene are the cause in several well-known growth failure disorders due to impaired endochondral bone formation such as achondroplasia and hypochondroplasia." (PMID 23155469, 2012). "Two mutations in FGFR3, G380R and G375C are known to cause achondroplasia, the most common form of human dwarfism." (PMID 22529939, 2012). "Activating mutations of the FGFR3 gene lead to craniosynostosis and multiple types of skeletal dysplasia with varying degrees of severity: thanatophoric dysplasia (TD), achondroplasia and hypochondroplasia." (PMID 19898608, 2009). "Achondroplasia in humans is most frequently due to constitutive activation mutations within the transmembrane domain of FGFR3." (PMID 18940000, 2008). "For instance, different germline FGFR3 (MIM: 134934) variants cause Achondroplasia (MIM: 100800), Hypochondroplasia (MIM: 146000), and other disorders; timely diagnosis of FGFR3-related skeletal dysplasia is essential for timely management of complications and genetic counseling." (PMID 41443197, 2026). "Perturbations in these programs, exemplified by mutations in Fgfr3, Sox9, and Dlx5, underlie region-specific skeletal dysplasias, such as achondroplasia, campomelic dysplasia, and split-hand/foot malformation, demonstrating the lasting impacts of embryonic patterning errors." (PMID 41596573, 2026). "Some, like osteogenesis imperfecta (OI), are primarily caused by mutations in structural proteins of the extracellular matrix, type I collagen in this case, whereas others are caused by mutations in components of the major signaling pathways, such as in the FGFR3, which causes achondroplasia (ACH)." (PMID 40565081, 2025). "Substantial progress has been made in recent years in the study of CNP and their role in skeletal disorders, particularly achondroplasia, which is caused by a gain-of-function mutation in FGFR3 that results in constitutive activation of FGFR3 and the downstream MEK/ERK MAPK pathway." (PMID 40430081, 2025). "Our findings may possess therapeutic potential, particularly for conditions such as achondroplasia resulting from activating mutations in FGFR3." (PMID 40581360, 2025). "Fgfr3 is a transmembrane receptor tyrosine kinase essential for regulating cell growth and differentiation during skeletal development, with mutations associated with disorders such as achondroplasia." (PMID 40581360, 2025). "Additionally, the use of the latest version of the reference rabbit genome enabled the identification of a genomic region containing FGFR3, a gene linked to achondroplasia." (PMID 40607659, 2025). "Achondroplasia, a rare disease that is caused by an activating mutation in the fibroblast growth factor receptor 3 (FGFR3) gene, affects endochondral ossification and disrupts long bone growth, leading to skeletal disproportion with short stature (125 to 134 cm average adult height)." (PMID 39062238, 2024). "Mutations in FGFR3 have been associated with achondroplasia." (PMID 38684708, 2024). "Achondroplasia (ACH) is a skeletal dysplasia characterized by short-limbed short stature caused by the gain-of-function mutations in the fibroblast growth factor receptor 3 (FGFR3) gene." (PMID 38544920, 2024). "In addition to craniosynostosis, mutations in FGFR3 are also associated with achondroplasia, which has also been linked to CM1." (PMID 39458107, 2024). "Advanced paternal age increases the risk of transmitting de novo germline mutations, particularly missense mutations activating the receptor tyrosine kinase (RTK) signalling pathway, as exemplified by the FGFR3 mutation, which is linked to achondroplasia (ACH)." (PMID 38397181, 2024).
achondroplasia (continued). "Achondroplasia is the most common of the skeletal dysplasias that cause fatal and disabling growth and developmental disorders in children, and is caused by a mutation in the fibroblast growth factor receptor, type 3 gene(FGFR3)." (PMID 38281003, 2024). "The p.Gly375Cys variant of FGFR3 gene may serve as a vital target for the diagnosis of severe achondroplasia." (PMID 37076826, 2023). "For example, case NO.4 was achondroplasia caused by a missense variant of the FGFR3 gene." (PMID 36797717, 2023). "In case 1b, the mother was affected by achondroplasia caused by a common variant, FGFR3 c.1138G>A." (PMID 37829280, 2023). "Achondroplasia is an autosomal dominant genetic disease representing the most common form of human skeletal dysplasia: almost all individuals with achondroplasia have identifiable mutations in the fibroblast growth factor receptor type 3 (FGFR3) gene." (PMID 36672940, 2023). "Achondroplasia is a rare genetic disorder caused by a mutation in the fibroblast growth factor receptor 3 (FGFR3) gene, which leads to a gain-of-function of the FGFR3 gene, a crucial regulator of bone development that physiologically inhibits chondrocyte growth." (PMID 37404559, 2023). "Finally, achondroplasia is associated with fibroblast growth factor receptor 3 gene mutations and fibroblast growth factor signaling." (PMID 36362274, 2022). "Importantly, FGF9 has high affinity for its receptor, FGFR3, and, as discussed later in this review, over-activating mutations in FGFR3 in humans and mice cause achondroplasia and midfacial hypoplasia." (PMID 35887171, 2022). "Similarly, patient F8317 died of severe skeletal dysplasia caused by a known achondroplasia-related FGFR3 variant inherited from both affected parents." (PMID 34645488, 2021). "FGFR3 activation causes dephosphorylation and inactivation of GC-B, but the contribution of GC-B dephosphorylation to achondroplasia (ACH) is unknown." (PMID 33784257, 2021). "Mutations in FGFR3 cause achondroplasia, a frequent form of dwarfism." (PMID 34071546, 2021). "The FGF receptors FGFR2 and FGFR3 show striking paternal age effects for the specific mutations that cause Apert's syndrome and achondroplasia, respectively, and these mutations show compelling evidence for clonal expansion of SSCs through inappropriate FGF signalling." (PMID 33107118, 2021). "Finally, targeting activating FGFR3 mutations in achondroplasia with FGFR inhibitors is another example worth noting, although the data here are from animal models only." (PMID 32066498, 2020). "The inhibitory activity of FGFR3 on growth plate chondrocytes explains the pathogenic consequences of gain-of-function mutations in FGFR3 in suppressing pre-pubertal skeletal growth in achondroplasia and related chondrodysplastic disorders." (PMID 32369771, 2020). "Most of the patients with the typical clinical features of achondroplasia have a spontaneous point mutation that results in a glycine to arginine substitution at amino acid 380 (G380R) located in the transmembrane domain of FGFR3." (PMID 33370388, 2020). "Although mutations at FGFR2 c.755 are a representative model for selfish mutations in general, further studies will be required to confirm the findings in other genes such as FGFR3 (associated with achondroplasia and thanatophoric dysplasia) and HRAS (associated with Costello syndrome)." (PMID 31348830, 2019). "Furthermore, 99% of all achondroplasia cases are caused by mutations in the FGFR3 gene, and c.1144G > A (p.Gly382Arg) is the most common pathogenic mutation." (PMID 31299979, 2019). "Achondroplasia, primarily a failure of endochondral ossification in the growth plate of cartilage, defined to be associated with pathogenic mutations in the transmembrane segment of FGFR3 gene." (PMID 28679403, 2017).
achondroplasia (continued). "Ongoing clinical trials have shown that in patients with achondroplasia, in which skeletal dysplasia is caused by a constitutively active form of FGFR3, stimulation of NPR2 by subcutaneous injection of a hydrolysis-resistant analog of CNP increases bone length." (PMID 29199951, 2017). "When achondroplasia is suspected, prenatal molecular diagnosis can be employed to evaluate for the specific G380R mutation, however sequencing of FGFR3 may be preferred if hypochodroplasia is on the list of differential diagnoses." (PMID 28321190, 2017). "Achondroplasia is the most common form of human short-limbed dwarfism and is one of a spectrum of diseases caused by mutations in the Fibroblast Growth Factor Receptor 3 (FGFR3) gene." (PMID 26693369, 2015). "However, additional FGFR3 mutations have been detected in hypochondroplasia, achondroplasia with developmental delay, and acanthosis nigricans, Muenke craniosynostosis and Crouzon syndrome with acanthosis nigricans." (PMID 25530967, 2014). "However, knocking in FGFR3 with achondroplasia mutation in cartilage of transgenic mice produced a small mouse with short bones, a phenotype similar to those seen in human achondroplasia." (PMID 25530967, 2014). "Likewise, activating mutations in FGFR3 are found in the transmembrane and the tyrosine kinase domains e.g. in achondroplasia, thanatophoric dysplasia type I (TDI) and type II (TDII)." (PMID 23527311, 2013). "The gain-of-function mutant of Fgfr3 causes achondroplasia, Sox9 controls chondrocyte differentiation via Sox5 and Sox6 expression, and Ihh is a master gene of bone development under BMP control, suggesting that Slc39a13 exerts a profound influence on genes crucial to chondrocyte differentiation." (PMID 18985159, 2008). "However, point mutations in the second tyrosine kinase domain of FGFR3 can result in lethal thanatophoric dysplasia or severe achondroplasia with developmental delay and acanthosis nigricans." (PMID 18940000, 2008). "Achondroplasia (ACH) is an autosomal-dominant disorder caused by gain-of-function mutations in the fibroblast growth factor receptor 3 gene (FGFR3)." (PMID 40134702, 2025). "Achondroplasia, the most common chondrodysplasia in humans, is caused by one of two gain of function mutations localized in the transmembrane domain of fibroblast growth factor receptor 3 (FGFR3) leading to constitutive activation of FGFR3 and subsequent growth plate cartilage and bone defects." (PMID 37747411, 2025). "Indeed, achondroplasia is caused by a gain-of-function mutation in the fibroblast growth factor receptor 3 (FGFR3) gene, a member of the tyrosine kinase family, resulting in prolonged activation of RAS/MAPK and alteration of chondrocyte proliferation and differentiation at the growth plate level." (PMID 37863846, 2024). "Achondroplasia (ACH), the most common form of disproportionate short stature, is caused by a pathogenic variant in the fibroblast growth factor receptor 3 gene." (PMID 34983594, 2022). "Four other short stature conditions similar to ACH are also caused by FGFR3 mutations, i.e., hypochondroplasia, SADDAN (severe achondroplasia with developmental delay and acanthosis nigricans) and thanatophoric dysplasia type I and type II." (PMID 35710503, 2022). "Autosomal dominant mutations in FGFR3 causing achondroplasia (ACH) (MIM #100800) were found in 13 of our cohort." (PMID 35250876, 2022). "Abnormal changes in IVD have been observed in mouse model mimicking human achondroplasia (ACH), a genetic skeletal disease caused by FGFR3 gain-of-function mutations." (PMID 35659742, 2022). "A gain-of-function mutation in the fibroblast growth factor receptor 3 gene (FGFR3) results in achondroplasia (ACH), the most frequent form of dwarfism." (PMID 35078974, 2022).
achondroplasia (continued). "Moreover, the important role of the RAS/MAPK pathway in growth plate development has been documented in achondroplasia and hypochondroplasia, the most common primary skeletal dysplasias in humans, which are caused by gain of function variants of the fibroblast growth factor receptor 3 (FGFR3)." (PMID 34149626, 2021). "Achondroplasia (ACH; the most common form of dwarfism in humans) is caused by a missense mutation in the gene coding for fibroblast growth factor receptor 3 (FGFR3); the mutation activates the receptor and its downstream signaling pathways." (PMID 33737326, 2021). "Achondroplasia (ACH) is a common skeletal dysplasia with short-limbed short stature caused by gain-of-function mutations in fibroblast growth factor receptor 3 (FGFR3)." (PMID 35118060, 2021). "Achondroplasia (ACH) is a disease caused by a missense mutation in the FGFR3 (fibroblast growth factor receptor 3) gene, which is the most common cause of short stature in humans." (PMID 34070375, 2021). "Gain-of-function mutations of the FGFR3 gene result in ACH, as well as related chondrodysplasias including thanatophoric dysplasia (TD) and severe achondroplasia with developmental delay and acanthosis nigricans (SADDAN)." (PMID 32079226, 2020). "Achondroplasia (ACH) is the most common short-limbed skeletal dysplasia caused by activating mutations in the fibroblast growth factor receptor 3 (FGFR3) gene." (PMID 32282831, 2020). "Specific human disease conditions such as achondroplasia, where underlying genetic causes (FGFR3 gain-of-function mutations) are defined, may have specific molecular mechanistic similarities to FGF4 overexpression and IVDD (potentially signaling through FGFR3) in dogs." (PMID 32793650, 2020). "Achondroplasia (ACH), the most common form of short‐limbed skeletal dysplasia, is caused by gain‐of‐function mutations in the fibroblast growth factor receptor 3 (FGFR3) gene." (PMID 31975530, 2020). "The discovery that achondroplasia (a well-known skeletal dysplasia in which serum phosphate is unaffected) is caused by activating mutations of an FGF23 receptor (FGFR3), indicated that FGF23-related pathways may affect skeletal development in phosphate-independent manners." (PMID 30808384, 2019). "Achondroplasia (ACH), the most common genetic dwarfism in human, is caused by a gain-of function mutation in fibroblast growth factor receptor 3 (FGFR3)." (PMID 28230213, 2017). "Achondroplasia (ACH) is an autosomal dominant disorder generally resulting from a specific gain-of-function mutation (G380R) in the fibroblast growth factor receptor 3 (FGFR3)." (PMID 28321190, 2017). "However, in a study involving mice in which one allele of the Fgfr3 gene was replaced with a constitutively active form, as occurs in achondroplasia, it was found that treatment with the CNP analog increased the growth rate of cultured tibia only partially, from ~40% to~70% of wild type." (PMID 29199951, 2017). "Achondroplasia (ACH) is the most common short-limbed skeletal dysplasia caused by gain-of-function mutations in the fibroblast growth factor receptor 3 (FGFR3)." (PMID 28785080, 2017). "Owing to the reported dysmorphic features and to exclude the hypothesis of achondroplasia, karyotype, fibroblast growth factor receptor 3 (FGFR3) mutation analysis and array based genomic comparative hybridization (array CGH) were conducted, obtaining normal results." (PMID 23672850, 2013). "Finally, whilst presentation in the third trimester is uncommon with widespread use of routine second trimester anomaly scanning, targeted NIPD screening for mutations in the FGFR3 gene could readily distinguish TD from achondroplasia." (PMID 23408600, 2013). "Recifercept, a recombinant soluble FGFR3 decoy protein originally developed for achondroplasia, functions by binding FGF ligands and dampening FGFR3-mediated signaling." (PMID 41584352, 2026).